SIRT7 (sirtuin 7)
Diseases named in the same sentence as SIRT7 in open-access papers (continued):
Sharing a sentence is not in itself a finding about the gene and the disease.
cancer (continued). "Though increasing substrates of FBXO7 in cancer and nervous system diseases have been detected, such as Sirtuin 7 (SIRT7), cyclin-dependent kinases (CDK6) and Ubiquitously eXpressed Transcript isoform 2 (UXTV2)." (PMID 37344480, 2023). "Emerging evidence also implicates SIRT7 in cancer biology by inducing H3K18 deacetylation for maintaining fundamental properties of the cancer cell phenotype." (PMID 36678616, 2023). "Inactivate SIRT7 impairs cancer transformation, increases chemosensitivity, and reverses metastatic phenotypes in cancer." (PMID 36678616, 2023). "Previous studies have also demonstrated that SIRT7 acts as an oncogene or anti-cancer gene in the progression of diverse cancers, regulating cell proliferation and autophagy, and serves as a stress regulator in physiological homeostasis." (PMID 37957720, 2023). "Considering that SIRT1 and SIRT6 act as tumor suppressors, SIRT7 seems to have the opposite role in cancer." (PMID 36429037, 2022). "SIRT7 promotes cancer cell proliferation, colony formation, and motility by activating MAPK, ERK, and MEK pathways, increasing vimentin and fibronectin expression, and reducing E-cadherin and β-catenin expression." (PMID 35585284, 2022). "Recently, increasing evidence has demonstrated that SIRT7 expression is altered in many human cancers, which suggests its important functions in various cellular events with a potential impact on oncogenic transformation and tumour biology." (PMID 35422493, 2022). "Next, we detected the expression levels of SIRT7 in pancreatic cell lines and found that the expression of SIRT7 was higher in cancer cells (AsPC-1, BxPC-3, PANC-1, MiaPaCa-2, CFPAC-1) than in normal ductal epithelial cell (hTERT-HPNE)." (PMID 35422493, 2022). "When SIRT7 is downregulated, EZH2 is acetylated and active, causing a shift from the epithelial to the mesenchymal phenotype, with an increase in cancer cell motility." (PMID 35745656, 2022). "The expression levels of SIRT7 were elevated in the majority of analyses across all types of cancer." (PMID 35136826, 2022). "SIRT6 and SIRT7 were mainly expressed in cancer cells, enterocytes, MSCs, and goblet cells, when SIRT7 also expressed in PMCs and neck-like cells." (PMID 36324577, 2022). "In cancer, SIRT1 and SIRT6 act as tumor suppressors, whereas SIRT7 is responsible for tumor phenotype maintenance, and its expression is increased in many cancers." (PMID 36012298, 2022). "SIRT7 is a classic NAD+-dependent deacetylase that stabilizes the transformed state of cancer cells." (PMID 35422493, 2022). "A typical example is the notorious cancer promoter, SIRT7, which is a member of the NAD+-dependent deacetylase Sirtuin family." (PMID 36291918, 2022). "Emerging evidence has shown that epigenetic factor SIRT7 is involved in various aspects of cancer biology, while inactive SIRT7 reverses human cancer phenotype and suppresses tumor growth." (PMID 35174171, 2021). "SIRT7 fine-tunes the balance between energy stress and oncogenic signals, thus providing a potential therapeutic strategy against multiple cancers and age-related diseases." (PMID 34433808, 2021). "Since cancer is widely recognized as an age-related disease and the incidence of most cancers increases with age77, the roles of SIRT7 in cancers should be clearly elucidated if considering its further therapeutic application for aging." (PMID 34433808, 2021). "Similar to Sirt6 and Sirt7, Sirt3 was also related to DNA damage repair signaling pathway, which is one of core mechanism of cancer radioresistance." (PMID 34405009, 2021). "SIRT3 and SIRT7 expression was correlated with high proliferation rates in the GCT samples, and these two SIRT family members have also been implicated in different cancers." (PMID 33669567, 2021). "In chromatin, SIRT7 selectively deacetylates histone H3 lysine 18 (H3K18Ac), which serves to maintain the cellular transformation ability of human cancer cells and tumour formation in vivo." (PMID 34129782, 2021).
cancer (continued). "Our data highlight the potential benefits of targeting SIRT7 using small-molecule activators in cancer therapy and age-related diseases." (PMID 34433808, 2021). "As the point at which EGF signaling and the energetic stress response converge, the GSK3β–SIRT7 axis represents an ideal therapeutic target in various cancers." (PMID 34433808, 2021). "It has been also shown that 5-fluorouracil stimulates radiosensitivity via SIRT7 breakdown to beneficence the cell death pathway in cancer cells." (PMID 33705642, 2021). "Cancer cells overexpressing ectopic SIRT7-WT or SIRT7-2E displayed much higher sensitivity to DXR treatment than SIRT7-2A cells." (PMID 34433808, 2021). "In sharp contrast, binding of SIRT1 to SIRT7 is fundamental to promote the formation of ribosomal DNA heterochromatin and to repress E-cadherin expression, thus stimulating cancer metastasis." (PMID 34573343, 2021). "SIRT7 acts as a potent oncogene in different malignancies and is upregulated in numerous human cancers." (PMID 34573343, 2021). "Inactive SIRT7 reverses aggressive cancer phenotypes, inhibits metastasis, and sensitizes cancer cells to therapy." (PMID 35174171, 2021). "Among all, Sirt1, Sirt6 and Sirt7 was demonstrated to involve in DNA damage repair, the over-activation of which accounts mainly for radioresistance of cancer 19,20." (PMID 34405009, 2021). "In agreement with a tumor-promoting role for SIRT7, our study found that SIRT7 was significantly up-regulated in multiple cancers." (PMID 32158696, 2020). "SIRT7 seems to have a dual role in cancer cells by targeting substrates (e.g., H3K18ac, ATM, and SMAD4)." (PMID 32404984, 2020). "Previous studies have shown that SIRT7 is regulated by various miRNAs in the development and progression of different types of cancer." (PMID 33274232, 2020). "For cancer stages, the higher expression of SIRT7 in late-stage cancers compared to early stages suggests a possible role of SIRT7 in cancer progression and invasion." (PMID 32528869, 2020). "A recent report showed that 5-fluorouracil (5-FU) induces radio-sensitivity via SIRT7 degradation, which promotes cell death during cancer cell radiotherapy." (PMID 32527012, 2020). "Through histone deacetylation of H3K18 at specific promoters, SIRT7 controls a tumor-suppressive gene expression program that stabilizes the transformed state of cancer cells." (PMID 33274232, 2020). "It has been revealed that sirtuin 7 (SIRT7) can suppress the migration of cancer cells through inhibiting TGF-β signaling via Smad4 degradation." (PMID 32752069, 2020). "SIRT7 expression was significantly correlated with sample type, subclass, cancer stage, menopause status, age, nodal status, estrogen receptor (ER), progesterone receptor (PR), and triple-negative status." (PMID 32528869, 2020). "The downregulation of SIRT7 affects the cell cycle, leading to a substantial increase in cancer cells in G1/S phase, inhibiting growth." (PMID 32670359, 2020). "SIRT7 has an oncogenic role in tumorigenesis, activating cancer proliferation via deacetylation of specific promoters of different tumor suppressor genes." (PMID 30761005, 2019). "SIRT6 and SIRT7 are both nuclear proteins with deacetylase activity and function as both tumor suppressor and promotor in cancer, including OC." (PMID 31572453, 2019). "Inactivation of SIRT7 reverses the malignant phenotype of cancer cells and decreases their tumorigenicity." (PMID 31121824, 2019). "Increased SIRT7 expression is observed in many human cancers and growing evidence suggests that it plays important functions in fundamental cellular programs that impact oncogenic transformation and tumor biology." (PMID 31196136, 2019). "Deacetylation of H3K18Ac by SIRT7 is crucial for maintaining essential features of cancer cells, including escape from contact inhibition and anchorage-independent growth." (PMID 31121824, 2019).
cancer (continued). "SIRT7 is possibly the least understood mammalian sirtuin, but its activity is important for human disease, particularly cancer." (PMID 31196136, 2019). "It has been demonstrated that SIRT7 is essential for maintaining the cancer cell phenotype and stabilizing the tumorigenicity of tumors by selective deacetylation of H3K18Ac." (PMID 31121824, 2019). "As an oncogene, SIRT7 inhibition reduces cancer-cell growth, represses colony formation and cancer-cell metastasis and increases cancer-cell apoptosis." (PMID 30510540, 2018). "Even though the definitive function of SIRT7 is uncertain, many consider SIRT7 as a cancer biomarker or a predictor of prognosis." (PMID 30510540, 2018). "Although previous reports studied the role and function of SIRT7 in various cancers, they mainly focused on tumor growth (e.g., cell proliferation, apoptosis, and cell cycle arrest)." (PMID 30001742, 2018). "The researchers concluded that SIRT7 inhibits cancer-cell apoptosis by up-regulating Bcl-2 and NF-κB levels." (PMID 30510540, 2018). "Sirt7 is upregulated in different types of human cancers where it correlates with a more aggressive phenotype and poor prognosis." (PMID 29963979, 2018). "Although ample evidence supports the involvement of SIRT7 in carcinogenesis, SIRT7 exhibits opposing roles in different cancer types." (PMID 30510540, 2018). "Again, in breast cancer Sirt7 expression has been found elevated in early disease stages compared to advanced cancer." (PMID 30304806, 2018). "SIRT7 is up- regulated in the majority of cancers, including colorectal, gastric, thyroid, node-positive breast, bladder, ovarian and cervical cancers, hepatocellular and epithelial prostate carcinoma, where it acts as an oncogene." (PMID 30510540, 2018). "Over-expression of SIRT7 led to p21WAF1/Cip1 suppression and induction of cyclin D1 expression to promote cancer-cell growth." (PMID 30510540, 2018). "Second, SIRT7 influences ribosome biogenesis to meet the high biosynthetic and metabolic needs of cancer cells." (PMID 30510540, 2018). "Recent findings from the TCGA database suggest that SIRT7 expression is tightly correlated with the development of various types of cancer." (PMID 30510540, 2018). "We analyzed the expression of SIRT7 by immunohistochemistry in 57 patients comparing healthy with adjacent cancer tissue." (PMID 29100388, 2017). "A study of drug-resistant cancer cells showed that SIRT7 inhibition increases stress resistance and modulates insulin/IGF-1 signaling pathways." (PMID 27659520, 2017). "Elevated levels of Sirt7 have been previously observed in several cancers including breast, liver, pancreas and colon." (PMID 29100388, 2017). "Thesefindings provide evidence that SIRT7 inactivation in cancer cells specificallyprevents metastasis in vivo, independent of changes in intrinsic tumorcell proliferative capacity." (PMID 25923013, 2015). "RPS7 is one among the select subset of genes that have been demonstrated to be transcriptionally repressed by SIRT7-mediated H3K18 hypoacetylation on their promoters in cancer cells." (PMID 26442981, 2015). "To further explore the clinicalrelevance of SIRT7 over-expression, we analyzed human cancer datasets from thecBioportal database for Cancer Genomics." (PMID 25923013, 2015). "Our findings fit well with recent evidence that SIRT7 depletion reduces metastasis bycolorectal cancer cells in mouse xenograft metastasis models." (PMID 25923013, 2015). "Together, these results demonstrate that SIRT7 is a positiveregulator of cancer cell migration and invasion abilities." (PMID 25923013, 2015). "Here,we identify the chromatin regulatory Sirtuin factor SIRT7 as a key regulator ofmetastatic phenotypes in both epithelial and mesenchymal cancer cells." (PMID 25923013, 2015). "In contrast to this observation, SIRT7 has been characterized as an oncogene which selectively deacetylates histone H3 at lysine 18 to maintain tumorigenic potential in cancer cells." (PMID 25907989, 2015).
cancer (continued). "ThroughH3K18 deacetylation at specific promoters, SIRT7 controls a tumor suppressive geneexpression program that stabilizes the transformed state of cancer cells." (PMID 25923013, 2015). "Here, we have uncovered a role for SIRT7 in promoting acquisition of an invasivephenotype in both epithelial and mesenchymal cancer cells." (PMID 25923013, 2015). "Together with previous work, our findingshighlight the broad role of SIRT7 in maintaining the metastatic cellular phenotypein diverse cancers." (PMID 25923013, 2015). "It has recently been demonstrated that SIRT7 is a selective H3K18Ac deacetylase that mediates transcriptional repression and stabilizes the cancer cell phenotype." (PMID 25416589, 2014). "SIRT7 plays a critical function in maintaining properties of cancer cells, including escape from cell contact inhibition and anchorage-independent growth." (PMID 25486244, 2014). "Targeting SIRT7 may offer new therapeutic strategies for various cancers, particularly those with high SIRT7 expression, as SIRT7 functions in a context-dependent manner in cancer regulation." (PMID 41642899, 2026). "Therefore, this study aims to evaluate the pan-cancer significance of SIRT7 through integrated computational approaches." (PMID 41642899, 2026). "For instance, in CRC, SIRT7 activity impairs cancer cell growth and invasion." (PMID 39215785, 2025). "SIRT7 plays a crucial role in multiple human diseases, particularly cancer." (PMID 40165597, 2025). "In addition, SIRT7 attenuates the transcription of specific tumour-suppressor genes and induces rRNA production for the metabolic needs of the cancer cell." (PMID 40941028, 2025). "Through these complementary activities, SIRT7 may enhance global protein synthesis and fine-tune the translation of oncogenes and tumor suppressors, thereby contributing to cancer progression." (PMID 41471367, 2025). "Further exploration of SIRT7‐targeting strategies could lead to innovative treatments for cancer and other pathologies." (PMID 40165597, 2025). "Similar to other sirtuins, SIRT7 has a double‐faced role in cancer." (PMID 39215785, 2025). "However, little is known about the molecular mechanisms governing SIRT7 function, and recent studies underscore that its role in cancer is poorly understood and highly context-dependent, leading to both tumor promotion and tumor suppression." (PMID 39900593, 2025). "Despite being less extensively studied than SIRT5, SIRT7's potential enzymatic activity and cellular function may play a significant role in cancer metabolism." (PMID 39781339, 2025). "A modulator of SIRT5 and SIRT7 has been developed to intervene in cancer, with promising results." (PMID 40867281, 2025). "Accordingly, SIRT7 inhibitors have been proposed as potential epigenetic cancer chemotherapy." (PMID 39900593, 2025). "SIRT7 may also influence anti-cancer immunity through its central role in maintaining genomic integrity, thereby positioning it as a potential mediator at the intersection between genome stability and immune surveillance." (PMID 41471367, 2025). "Furthermore, high H3K18 deacetylation by SIRT7 enhances persistence of the malignant phenotype of cancer cells." (PMID 40941028, 2025). "SIRT7 was identified as a histone deacetylase at lysine 18 of H3 (H3K18) that regulates the transformed state of cancer cells, but subsequent studies have shown that SIRT7 also has multiple types of deacylase activity, including debutyrylation and desuccinylation." (PMID 40243935, 2025). "This interconnected regulatory network suggests that the complex and context-dependent role of SIRT7 in cancer progression may, in part, arise from the combined influence of these processes on the immune–tumor interface." (PMID 41471367, 2025). "In addition, SIRT7 can attenuate transcription of specific tumor-suppressor genes and has the ability to produce rRNA for the metabolic needs of the cancer cell." (PMID 40149343, 2025).
cancer (continued). "SIRT7 depletion reduces cancer cell proliferation and enhances 5-FU-induced apoptosis." (PMID 41425553, 2025). "Recent studies have highlighted the role of SIRT7‐mediated desuccinylation in cancer biology." (PMID 40586636, 2025). "Further research is warranted to determine whether similar SIRT7-dependent mechanisms operate in cancer cells and thereby influence anti-cancer immune responses." (PMID 41471367, 2025). "This function may explain the elevated SIRT7 expression in cancer and its role in maintaining the transformed phenotype of cancer cells." (PMID 40165597, 2025). "Given the critical role of the Th17/Treg axis in tumor immunity, these findings suggest that SIRT7 may indirectly modulate anti-cancer immune responses through this pathway." (PMID 41471367, 2025). "In general, SIRT7's involvement in various cellular processes, such as DNA replication, chemoresistance, and mitochondrial function, underscores its therapeutic potential across a range of cancers and diseases." (PMID 40165597, 2025). "Given that enhanced glycolysis in cancer cells suppresses anti-tumor immunity through metabolic competition with T cells, it is plausible that SIRT7 upregulation in certain malignancies may indirectly promote immune responses by limiting glycolytic flux." (PMID 41471367, 2025). "Clarifying these functions will be crucial in determining whether targeting SIRT7 localization in this compartment could pave the way for innovative anti-cancer therapies." (PMID 39036727, 2024). "In addition, SIRT7 exerts epigenetic control over the expression of specific genes involved in cancer progression, further contributing to the malignant phenotype 167." (PMID 39479446, 2024). "This evidence suggests that SIRT7 may exert tumor-suppressive roles in cancer initiation by controlling this mechanism although further research is warranted to support this claim." (PMID 38383727, 2024). "This event may synergize with altered SIRT7 expression that often occurs in cancer cells ultimately contributing to cancer progression." (PMID 38383727, 2024). "SIRT7 may exert some of its prosurvival functions in cancer by inhibiting ARF but other processes may contribute." (PMID 38870055, 2024). "The destabilization of ARF by SIRT7 may also influence other functions of ARF crucially involved in cancer progression." (PMID 39036727, 2024). "Thus, investigating the potential development of anti-cancer drugs targeting the SIRT7-AKT pathway seems to hold promise, so far, only in this specific malignancy." (PMID 38383727, 2024). "Moreover, the regulatory influence of SIRT7 extends to various cancer-related signaling pathways, highlighting its multifaceted role in modulating the tumor microenvironment." (PMID 39682281, 2024). "Furthermore, SIRT7 assumes a vital function in bolstering the viability of cancer cells upon exposure to the combined treatment of 5-fluorouracil (5-FU) and radiotherapy – a prevailing therapeutic modality targeting this malignancy." (PMID 38383727, 2024). "In contrast, the impact of SIRT7-dependent decrotonylation activity in cancer remains unexplored." (PMID 38383727, 2024). "In specific cancer cells, the abundance of specific RNA may prominently influence SIRT7 interactions and activities, ultimately influencing tumorigenesis." (PMID 38383727, 2024). "Moreover, inhibition of SIRT7 in cells derived from these tumors induces a significant deceleration in cancer cell growth, accompanied by a hindered capacity for tumor formation in mouse xenograft models." (PMID 38383727, 2024). "For instance, recent research has shown a correlation between altered SIRT7 expression and various human cancers, indicating its significant involvement in cellular processes that could contribute to oncogenic transformation and tumor biology." (PMID 39719443, 2024).